PDCD4 (programmed cell death 4)
Diseases named in the same sentence as PDCD4 in open-access papers (continued):
Sharing a sentence is not in itself a finding about the gene and the disease.
diabetes (8 papers, 2012 to 2025). "While BCAA intake may have potential benefits in cancer prevention and therapy, the upregulation of PDCD4 could pose a risk of worsening insulin resistance or diabetes." (PMID 41439995, 2025). "However, PDCD4-deficient mice are resistant to inflammatory diseases such as autoimmune encephalomyelitis and diabetes." (PMID 41439995, 2025). "Programmed cell death protein 4 (PDCD4) is known to be associated with diabetes." (PMID 36552599, 2022). "Other validated target of miR-21 are the fas ligand (Faslg), Pdcd4, and Tiam1 which are also related to diabetes." (PMID 25671565, 2015). "However, PDCD4 knockdown mice are resistant to inflammatory diseases such as autoimmune encephalomyelitis and diabetes." (PMID 41439995, 2025). "PDCD4 may play a role in differentiation and diseases such as diabetes and inflammation." (PMID 34606825, 2021). "The PDCD4-depleted mice developed spontaneous tumors, mostly B-lymphoma, and showed significantly shorter life spans than their wild-type siblings, although they were resistant to the induction of inflammatory diseases, such as autoimmune encephalomyelitis and diabetes." (PMID 33304903, 2020). "Programmed cell death 4 (PDCD4), an endogenous inhibitor of translation, has been identified as a target of miR 21, and it will be interesting to investigate the role of miR 21 in regulating ECM protein synthesis induced by diabetes." (PMID 22454628, 2012).
nasopharyngeal carcinoma (8 papers, 2013 to 2025). A carcinoma arising from the nasopharyngeal epithelium. "Up-regulation of miR-21 could enhance chemoresistance in nasopharyngeal carcinoma cells by targeting PDCD4 and Fas-L." (PMID 24788655, 2014). "On the other hand, low PDCD4 expression was significantly related with lymph node metastasis in head and neck malignancy, and PDCD4 upregulation could inhibit invasiveness of oral cancer and nasopharyngeal carcinoma cells." (PMID 27533461, 2016). "On the other hand, an additional target of miR-184, programmed cell death 4 (PDCD4), has been described to be a tumor suppressor by acting at the level of c-Myc and Bcl-2, inhibiting the cell proliferation and survival in nasopharyngeal cancer cells." (PMID 35883677, 2022). "Tumor suppressor PDCD4 modulates miR-184-mediated direct suppression of C-MYC and BCL2 blocking cell growth and survival in nasopharyngeal carcinoma." (PMID 32309578, 2016).
non-small cell lung carcinoma (8 papers, 2014 to 2025). A group of at least three distinct histological types of lung cancer, including non-small cell squamous cell carcinoma, adenocarcinoma, and large cell carcinoma. "PDCD4 overexpression has the capacity to restrict cell growth through its inhibitory role in the PI3K/Akt pathway in non-small-cell lung cancer, supporting our findings." (PMID 35295718, 2022). "Studies show that overexpression of miR-182 leads to chemoresistance of non-small cell lung cancer to cisplatin by downregulating PDCD4." (PMID 34525952, 2021). "PDCD4 is a functional target of miR-155 and regulates proliferation or invasion by targeting PDCD4 in non-small-cell lung cancer." (PMID 31620370, 2019). "This study aims to explore the effects of microRNA-21 (miR-21) on radiosensitivity in non-small cell lung cancer (NSCLC) by targeting programmed cell deanth 4 (PDCD4) and regulating PI3K/AKT/mTOR signaling pathway." (PMID 28423589, 2017). "Moreover the downregulation of miR-21 expression restrains non-small cell lung cancer cell proliferation and migration through upregulation of programmed cell death 4 protein." (PMID 26116834, 2015).
B-cell lymphoma (7 papers, 2014 to 2023). "PDCD4 is a major target of miR-21, an oncomiR in pre-B-cell lymphoma that post-transcriptionally downregulates PDCD4 in a variety of cancers." (PMID 32264925, 2020).
breast tumors (7 papers, 2014 to 2022). "In another study, elevated levels of PRMT5 were shown to reduce the tumour‐suppressor activity of PDCD4 in primary breast tumours by methylating its N‐terminal arginine residues, resulting in reduced patient survival." (PMID 33462997, 2021). "Collectively, these results link pluripotency factor signaling and the enhanced cell survival of MaCSCs, supporting roles of KLF4-miR-206 signaling for breast tumor cell survival, chemoresistance, and tumor initiation through the repression of PDCD4 and CX43." (PMID 26053033, 2015). "Furthermore, in human breast tumors, miR-21 has been shown to simultaneously downregulate multiple metastasis-related tumor suppressor genes, including programmed cell death 4 (PDCD4), encouraging cell invasion and metastasis." (PMID 36359024, 2022). "Inhibition of PKCε-Nanog signaling by downregulating PKCε with PKCε siRNA or silencing miR-21 with anti-miR-21 inhibitor results in PDCD4 up-regulation and causes IAP/MDR1 (P-gp) reduction, as well as apoptosis/cell death and chemosensitivity in breast tumor cells." (PMID 27070574, 2016). "Therefore, immunohistochemical analysis was performed on over 3000 breast tumors to investigate the relationship among expression of eIF4A1, the helicase-modulating proteins eIF4B, eIF4E and PDCD4, and clinical outcome." (PMID 25611378, 2015). "These events contribute to the reduction of PDCD4 (the tumor suppressor protein), overexpression of IAP/MDR1 (P-gp), cell survival, and chemotherapeutic drug resistance in breast tumor cells." (PMID 27070574, 2016).
lung adenocarcinoma (7 papers, 2016 to 2024). A carcinoma that arises from the lung and is characterized by the presence of malignant glandular epithelial cells. "Exosomal miR-21 from A549 cells enhances osteoclastogenesis via targeting programmed cell death 4 (Pdcd4), and is associated with poor survival in lung adenocarcinoma patients." (PMID 33614495, 2020). "Lung adenocarcinoma cell-derived exosomal miR-21 also promotes osteoclast formation by targeting PDCD4." (PMID 34557095, 2021). "The expression levels of miR-21 and its downstream target protein PDCD4 were determined by real time PCR and florescence immunohistochemistry respectively in lung tissues from lung adenocarcinoma patients." (PMID 27323401, 2016).
lupus (7 papers, 2015 to 2024). "The downregulation of miR-31 contributed to impaired IL-2 production and signaling in lupus T cells, and the upregulation of miR-21 promoted T cell responses in lupus via targeting PDCD4." (PMID 34062726, 2021). "In this study, we have taken an unbiased approach to identify RBPs binding to the PDCD4 mRNA 3ʹUTR and have identified lupus antigen (La) as one of the interacting partners of the PDCD4 mRNA 3ʹUTRs." (PMID 33288677, 2021). "SLE patients also showed the similar tendency with MRL mice; the expression level of Ctse and IL10 mRNAs in CD4+ T cells is upregulated in lupus patients than healthy control, while PDCD4 mRNA lower tendency in lupus patients than healthy control." (PMID 30816218, 2019). "However, recent studies have reported a relationship between miR-21, PDCD4, and IL-10 in patients with systemic lupus erythematosus." (PMID 39100039, 2024). "In an in vivo study, silencing of miR‐21 under a tiny seed‐targeting locked‐nucleic acid (LNA) reversed splenomegaly resulted in approximately 20% de‐repression of programmed cell death 4 (PDCD4) in naïve CD4+ T cells and recovery of lupus mice." (PMID 35707883, 2022).
oral cancer (7 papers, 2010 to 2025). "A matrigel invasion assay showed that PDCD4 expression suppressed invasion, and siRNA-mediated PDCD4 loss was associated with increased invasive potential of oral carcinoma cells." (PMID 20831814, 2010). "However reduction of PDCD4 was marginally associated with nodal metastasis in oral cancers." (PMID 26867589, 2016). "Its higher expression correlated with the downregulation of Programmed Cell Death 4 (PDCD4), the tumor suppressor genes, and the increased invasive potential of oral carcinoma cells." (PMID 35571032, 2022). "Herein, we identified PDCD4 under-expression at both the mRNA and protein levels in primary patient OSCCs and oral cancer cell lines." (PMID 20831814, 2010). "Our data thus suggest a mechanism of PDCD4 regulation by miR-21, leading to PDCD4 under-expression in oral carcinoma." (PMID 20831814, 2010). "Our data show an association between the loss of PDCD4 expression, tumorigenesis and invasion in OSCC, and also identify a mechanism of PDCD4 down-regulation by microRNA-21 in oral carcinoma." (PMID 20831814, 2010). "In particular, they found that CSC-derived EVs (from oral cancer cell tumorspheres) are enriched with miR-21-5p, an important mediator in cisplatin resistance, and a direct regulator of tumor suppressor genes, such as programmed cell death 4 (PDCD4) and PTEN." (PMID 34638913, 2021). "We also demonstrated that PDCD4 is involved in invasion of oral carcinoma cells." (PMID 20831814, 2010).
oral squamous cell carcinoma (7 papers, 2010 to 2022). "For instance, lncRNA CASC2 acts as a ceRNA of miR-21 to up-regulate the expression of PDCD4 in oral squamous cell carcinoma." (PMID 31737900, 2020). "Upregulation of miR-21 by targeting PDCD4 could enhance tumor cell invasion in oral squamous cell carcinoma." (PMID 35402235, 2022). "In oral squamous cell carcinoma, this microRNA is part of the mechanism that regulates sensitivity to cisplatin, by targeting phosphatase and tensin homolog (PTEN), as well as programmed cell death protein 4 (PDCD4) genes." (PMID 31766478, 2019). "There are no current studies characterizing PDCD4 expression and its clinical relevance in Oral Squamous Cell Carcinoma (OSCC)." (PMID 20831814, 2010).
renal carcinoma (7 papers, 2015 to 2025). A carcinoma arising from the epithelium of the renal parenchyma or the renal pelvis. "Moreover, a potential association between PDCD4 and c-Jun signaling was suggested by the expression of miR-21, which promotes the migration, invasion, and angiogenic capacity of renal carcinoma cells." (PMID 36552834, 2022). "The molecular network confirmed by IPA also showed the key involvement of miR-181a and its association with renal cancer and dysfunction directly or indirectly via JNK1, FOXO1, FOXO3, and PDCD4." (PMID 41462911, 2025). "In a related study, it was demonstrated that miR-21 downregulates PDCD4 at the post-transcriptional level, leading to enhanced cell colony formation and proliferation in a nude mouse model of renal cancer." (PMID 39114567, 2024). "In renal cancer patients, it was negatively related between the PDCD4 expressions and the miR-106b-5p expressions." (PMID 33969128, 2021). "In ACHN and 786-O renal cancer cells, PDCD4 regulated AKT phosphorylation, leading to the migration or invasion of cancer cells via the up-regulation of the mammalian target of rapamycin complex 1 (mTORC1)." (PMID 27852288, 2016). "In addition, we found that miR-106b-5p negatively regulated PDCD4 in ccRCC cells and renal cancer patients." (PMID 33969128, 2021). "Furthermore, miR-21 promoted renal cancer cell hyperplasia and contributed to tumor cell transformation and metastasis, but also post-transcriptionally down-regulated the expression of the PDCD4 tumor suppressor gene." (PMID 26416448, 2015).
head and neck squamous cell carcinoma (6 papers, 2017 to 2025). A squamous cell carcinoma that arises from any of the following anatomic sites: lip and oral cavity, nasal cavity, paranasal sinuses, pharynx, larynx, and salivary glands. "For example, miR-21 can stabilize mature miR-499 post-transcriptionally, help suppress programmed cell death 4 (PDCD4), and subsequently promote cancer metastasis of head and neck squamous cell carcinoma." (PMID 38891080, 2024). "In a previous study, we showed that several miRNAs were deregulated in head and neck squamous cell carcinoma (HNSCC) clinical samples and that PDCD4 was regulated in a temporal manner." (PMID 31235478, 2019).
leukemia (6 papers, 2011 to 2025). A malignant (clonal) hematologic disorder, involving hematopoietic stem cells and characterized by the presence of primitive or atypical myeloid or lymphoid cells in the bone marrow and the blood. "We previously demonstrated that miR-15a-5p decreased apoptosis induced by DNR and/or cytarabine in leukemia by downregulating three pro-apoptotic target genes—PDCD4, ARL2, and BTG2—validating the implication of miR-15a-5p in drug resistance." (PMID 34068078, 2021). "We identified miR-21 was directly downregulated by RBP2 and found that miR-21 downregulated PDCD4 expression in leukemia cells." (PMID 25575817, 2015). "Collectively, NPMc+ may induce leukemia at both the transcription and translation level by regulating mislocalization and degradation of PDCD4, and disrupting its function in the cytoplasm and nucleus." (PMID 41234771, 2025). "In this study, we examined whether NPMc+ induces leukemia by interacting with PDCD4 and affecting its cytoplasmic and nuclear functions." (PMID 41234771, 2025). "Interestingly, both of our studies detected novel CXCL12-responsive AKT substrates, PDCD4 (pS457) and AKT1S1 (pT246), underscoring the potential role of AKT signaling and leukemias." (PMID 21949786, 2011).
liver cancer (6 papers, 2016 to 2025). An epithelial or non-epithelial malignant neoplasm that arises from the liver. "Inhibits the expression of SOCS1 and PDCD4, enhancing immune evasion mechanisms, promoting liver cancer cell growth." (PMID 39911396, 2025). "PDCD4 overexpression activated caspases 8, 9, 3, lead to the apoptosis of liver cancer cells." (PMID 32661236, 2020). "Therefore, PDCD4 may be a target for the treatment of liver cancer, although further studies both in vitro and in vivo are required." (PMID 30687637, 2018). "In comparison with the blank group, LFE regulated the mRNA expression levels of PTEN, PI3K, AKT, PDCD4, VEGFA, Caspase 9, Caspase 3, Bcl-2, Bax and Bad in liver cancer cells to different degrees." (PMID 36110518, 2022).
lymph node metastasis (6 papers, 2014 to 2022). "Loss of PDCD4 promotes tumor cells proliferation, migration and invasion, and is associated with lymph node metastasis and worse disease-free survival in patients with ER- and HER2-positive breast cancer." (PMID 35795053, 2022). "In addition, miR-21 targeting of PDCD4 (programmed cell death 4) is associated with lymph node metastasis and venous invasion." (PMID 27322246, 2016). "Low PDCD4 (P = 0.037) and PTEN (P < 0.001) were significantly associated with the regional lymph node metastasis of LSCC patients." (PMID 27533461, 2016). "Low PDCD4 expression was observed to be significantly related with poor differentiation and lymph node metastasis in LSCC patients." (PMID 27533461, 2016). "Among all clinicopathological parameters available, including gender, age, differentiation, and lymph node metastasis, only the tendency of cell differentiation tended to be obviously associated with PDCD4 expression, but no significance was observed (P = 0.056)." (PMID 25400316, 2014).
Obesity (6 papers, 2016 to 2025). Accumulation of substantial excess body fat. "It has been reported that PDCD4 deficiency prevents diet-induced obesity, adipose tissue inflammation, and insulin resistance in PDCD4-deficient (PDCD4 −/−) mice." (PMID 41439995, 2025). "The precise regulation of Nanog and Oct4 expression in ASCs might be partially influenced by programmed cell death 4 (Pdcd4), a protein translation suppressor linked to diet-induced obesity, WAT inflammation and insulin resistance." (PMID 38826152, 2024). "In addition, an elevation of UCP1 expression was confirmed in white adipose tissues from Pdcd4-deficient mice upon high-fat diet, which displayed increased energy expenditure and resistance to obesity as compared with wild-type obese mice." (PMID 27031966, 2016). "Collectively, our data suggest that Pdcd4 as a crucial regulator in SGs induced by ox-LDL or HFD maybe a potential target for mitigating SG-associated stress responses in obesity and related diseases." (PMID 27454120, 2016). "Pdcd4 has been demonstrated to be involved in HFD-induced obesity and associated stress responses." (PMID 27454120, 2016). "However, different from the protective function against tumor, Pdcd4 exerts unfavorable effects on ADSCs that contribute to obesity and associated metabolic syndromes." (PMID 27031966, 2016). "Thus, we provide a potential link between HFD-associated SGs and the pathogenesis of obesity and related diseases, indicating that Pdcd4 may be a novel therapeutic target for resolving SG-associated stress responses." (PMID 27454120, 2016). "Remarkably, Pdcd4 ablation also promotes the transition from white to beige adipocytes, resulting in augmented energy expenditure and resistance to obesity on a high-fat diet." (PMID 38826152, 2024). "A potential strategy to fight obesity is to promote white-to-beige transdifferentiation by downregulating the expression of Pdcd4 on ADSCs." (PMID 27031966, 2016). "We previously reported the implication of programmed cell death 4 (Pdcd4) in obesity-induced stress responses, but the possible link between Pdcd4 and SGs remains lacking." (PMID 27454120, 2016). "Recently, we have demonstrated the involvement of Pdcd4 in obesity, adipose inflammation, and atherosclerosis." (PMID 27454120, 2016). "Collectively, these findings reveal the novel actions of Pdcd4 on ADSC stemness, thereby adding new mechanisms on the list of diet-induced obesity and proposing potential approaches to the therapy for obesity and associated diseases." (PMID 27031966, 2016). "Pdcd4 deficiency leads to an obvious alleviation in high-fat diet (HFD)-induced adipose ER stress and hepatic oxidative stress, which are typical hallmarks of both obesity and cardiovascular events and link with inflammation on different levels." (PMID 27454120, 2016). "Furthermore, more biological processes regulating Pdcd4 expression remain to be further investigated and applied into the therapy for obesity-related pathologies." (PMID 27031966, 2016). "Programmed cell death 4 (Pdcd4) has been demonstrated to be involved in the development of obesity, but its possible roles in ADSC function and adipogenic capacity remain unclear." (PMID 27031966, 2016). "In conclusion, our data suggest that Pdcd4 plays an indispensible role in the pathogenesis of obesity and related diseases, thus may serve as a potential therapeutic target for these diseases." (PMID 27454120, 2016). "Therefore, ADSC-specific knockout or knockdown of Pdcd4 gene in adipose tissues is important to prevent the undesirable effects on other cells during obesity treatment." (PMID 27031966, 2016). "Based on our previous study, although WT and Pdcd4-/- mice were both fed on HFD, WT mice developed obesity, while Pdcd4-/- mice displayed lean phenotype." (PMID 27454120, 2016).
Obesity (continued). "Since ox-LDL is a typical biomarker for oxidative stress in HFD-induced obesity and related metabolic syndromes, we next used ox-LDL to treat primary peritoneal macrophages from WT and Pdcd4-/- mice, and examined TIA-1+ SGs in these macrophages." (PMID 27454120, 2016). "In the present study, we provide evidences that Pdcd4 acts as a controller that limits ADSC self-renewal and white-to-beige transdifferentiation, which could be another contributor to adipose dysfunction and obesity." (PMID 27031966, 2016). "Therefore, Pdcd4 might be involved in the exhaustion of ADSC stemness upon long-time HFD stimulation, which contributes to the development of pathological obesity." (PMID 27031966, 2016).